NLRC3 (NLR family CARD domain containing 3)
Description:
Negative regulator of the innate immune response. Attenuates signaling pathways activated by Toll-like receptors (TLRs) and the DNA sensor STING/TMEM173 in response to pathogen-associated molecular patterns, such as intracellular poly(dA:dT), but not poly(I:C), or in response to DNA virus infection, including that of Herpes simplex virus 1 (HSV1) (By similarity). May affect TLR4 signaling by acting at the level of TRAF6 ubiquitination, decreasing the activating 'Lys-63'-linked ubiquitination and leaving unchanged the degradative 'Lys-48'-linked ubiquitination. Inhibits the PI3K-AKT-mTOR pathway possibly by directly interacting with the posphatidylinositol 3-kinase regulatory subunit p85 (PIK3R1/PIK3R2) and disrupting the association between PIK3R1/PIK3R2 and the catalytic subunit p110 (PIK3CA/PIK3CB/PIK3CD) and reducing PIK3R1/PIK3R2 activation. Via its regulation of the PI3K-AKT-mTOR pathway, controls cell proliferation, predominantly in intestinal epithelial cells (By similarity). May also affect NOD1- or NOD2-mediated NF-kappa-B activation. Might also affect the inflammatory response by preventing NLRP3 inflammasome formation, CASP1 cleavage and IL1B maturation.
Synonyms: CLR16.2; NOD3; FLJ00348
Tractability: PROTAC: ubiquitination databases record sites on it; its protein half-life has been measured.
Gene: Protein-coding gene on chromosome 16 (3,539,033 to 3,577,403, reverse strand). Ensembl gene ENSG00000167984.
Subcellular location: Cytoplasm
Subcellular location (Human Protein Atlas): Cytosol; Centriolar satellite; Vesicles
Pathways (Reactome):
Immune System: IRF3-mediated induction of type I IFN
Gene Ontology:
Molecular function: protein binding; phosphatidylinositol 3-kinase regulatory subunit binding
Biological process: canonical NF-kappaB signal transduction; negative regulation of canonical NF-kappaB signal transduction; negative regulation of inflammatory response; negative regulation of interleukin-6 production; negative regulation of NLRP3 inflammasome complex assembly; negative regulation of non-canonical NF-kappaB signal transduction; negative regulation of tumor necrosis factor production; T cell activation; negative regulation of cytokine production involved in inflammatory response; negative regulation of epithelial cell proliferation; negative regulation of fibroblast proliferation; negative regulation of innate immune response; negative regulation of interferon-alpha production; negative regulation of interferon-beta production; negative regulation of phosphatidylinositol 3-kinase/protein kinase B signal transduction; negative regulation of immune system process; regulation of innate immune response
Cellular component: cytoplasm; cytosol; perinuclear region of cytoplasm
Genetic constraint (gnomAD): Loss-of-function variants: 57 observed, 51.27 expected, observed/expected ratio (o/e) 1.11, 90% interval 0.9 to 1.39. The synonymous counts are far from expectation, so gnomAD's model fits this gene poorly and the ratio says little. Missense variants: 1,358 observed, 1,143.1 expected, observed/expected ratio (o/e) 1.19, 90% interval 1.13 to 1.24. Synonymous variants: 612 observed, 519.94 expected, observed/expected ratio (o/e) 1.18, 90% interval 1.1 to 1.26.
Homologues: Orthologues: chimpanzee NLRC3 (99% identical), macaque NLRC3 (92% identical), pig NLRC3 (85% identical), dog NLRC3 (84% identical), guinea pig NLRC3 (84% identical), rat Nlrc3 (80% identical), mouse Nlrc3 (80% identical), rabbit NLRC3 (73% identical), tropical clawed frog nlrc3 (49% identical), zebrafish nlrc3 (36% identical). Paralogues in human: NLRC5 (23% identical), NLRP12 (22% identical), NLRP3 (20% identical), NOD2 (20% identical), NLRP4 (19% identical), NLRP5 (18% identical), NLRP14 (18% identical), NLRP9 (18% identical), NLRP7 (18% identical), NOD1 (17% identical), NLRP1 (17% identical), NLRP2 (17% identical), and 8 more.
Diseases named in the same sentence as NLRC3 in open-access papers:
NLRC3 is named in the same sentence as 53 diseases in open-access papers, as found by Europe PMC text mining. Sharing a sentence is not in itself a finding about the gene and the disease. The quoted sentences say what the papers report.
colorectal cancer (12 papers, 2016 to 2023). A primary or metastatic malignant neoplasm that affects the colon or rectum. "PI3K-AKT-mTOR and PI3K-AKT-FoxO3a/FoxO1 signal pathways are associated with the suppressive effect of NLRC3 on colorectal cancer." (PMID 36341336, 2022). "Several bioinformatics papers and some reports from detecting clinical specimens have demonstrated that NLRC3 is associated with the prognosis and malignancy of tumors (include colorectal cancer, Hepatocellular carcinoma, Gastric cancer, Bladder cancer and lung adenocarcinoma)." (PMID 36341336, 2022). "In a AOM-DSS inflammation-induced colorectal cancer model, defective inflammasome activation leads to loss of epithelial integrity, massive leukocyte infiltration, and increased chemokines expression in NLRC3−/− mice, NLRC3 seems important for the suppression of inflammation." (PMID 33425209, 2020). "In colorectal cancer, NLRC3 inhibits systemic inflammation, leading to a decrease in NLR value and an increase in anti-tumor lymphocytes-cytotoxic T lymphocytes." (PMID 35145917, 2022). "This reveals that NLRC3 has a potential tumor suppression effect in the malignant progression of colorectal cancer." (PMID 35145917, 2022). "This is similar to mouse model findings where it was found that NLRC3 knockouts are more likely to develop colorectal inflammation and colorectal cancer." (PMID 35145917, 2022). "NLRC3 mediates protection against colorectal cancer by inhibiting the activation of the mTOR signaling pathway." (PMID 35433762, 2022). "It was previously reported that NLRC3 prevents the growth of colorectal cancer by inhibiting PI3K-mTOR (mammalian target of rapamycin) pathway." (PMID 35145917, 2022). "NLRC3 has been proposed to inhibit the processes related to colorectal cancer through the regulation of cellular proliferation and apoptosis levels." (PMID 33406504, 2021). "It has been demonstrated that expression of NLRC3 is drastically reduced in the tumor tissues of patients with colorectal cancer compared to healthy tissues." (PMID 30271661, 2018). "Previous studies have confirmed that NLRC3 prevents colorectal cancer growth by suppressing the PI3K-mTOR signaling pathway and that it may suppress HCC progression by promoting CD8+ T-cell infiltration." (PMID 36808166, 2023). "For example, NLRC3 prevents colorectal cancer growth by suppressing the PI3K-mTOR signaling pathway and may suppress hepatocellular carcinoma (HCC) progression by promoting CD8+ T-cell infiltration." (PMID 36808166, 2023). "They found that the mRNA expression of NLRC3 as an inflammation checkpoint; NLRP1, NLRP3 and NLRC4 as the components of inflammasome and AIM2 were all decreased in colorectal cancer." (PMID 34571825, 2021). "The authors also reported that the reduction in NLRC3 and AIM2 mRNA expression in colorectal cancer cells was correlated with the progression of colorectal cancer." (PMID 34571825, 2021).
viral infection (8 papers, 2017 to 2025). "Therefore, in vivo studies assessing the resistance of NLRC3-deficient fish models to virus infection will provide deeper insights into its potential utility in resistant breeding." (PMID 39859554, 2025). "The binding ability of LvNLRC to viral nucleic acid and the intramolecular interaction mechanism remind us of the regulatory function of mammalian NLRC3 on STING signaling pathway in response to viral infection." (PMID 40825070, 2025). "The precise regulatory mechanism of IFN response has been extensively studied, while the regulatory role of NLRC3 on host IFN response is poorly understood in grass carp, which have long-term suffered from viral diseases." (PMID 39859554, 2025). "During viral infection, TLR9 and STING activated the NF-κB signaling pathway, which attenuated the expression of NLRC3." (PMID 36341336, 2022). "Moreover, the impact of NLRC3 on the modulation of IFN-I pathways during viral infections has not been thoroughly explored in aquatic organisms." (PMID 39859554, 2025). "NLR Family CARD Domain Containing 3 (NLRC3) was shown to be a negative regulator, which negatively regulates diverse aspects of host antiviral immunity including STING, type I IFN and TLR-induced NF-κB signaling to attenuate overzealous inflammation following virus infection." (PMID 28714877, 2017).
Autoimmunity (4 papers, 2022 to 2024). The occurrence of an immune reaction against the organism's own cells or tissues. "Existing research has identified NLRC3 as a factor involved in host immunity against pathogens such as bacteria and parasites, attenuating autoimmunity by downregulating antigen-presenting function of dendritic cells through the p38 signaling pathway." (PMID 37312878, 2023). "As revealed by evidencing studies, NLRC3 increases many genes related to the activation of Th1/Th17/T cells, such as Ifng, Tnf, Il17f, Il17a, and Tbx21; also, study reveals that Nlrc3 expression in T cells inhibits autoimmunity as well as CD4+ T cell responses specific for virus." (PMID 38436712, 2024). "NLRC3 is expressed both in CD4+ T cells and in DCs and limits autoimmunity by different pathways." (PMID 35619184, 2022). "Furthermore, NLRC3 activation in T cells and dendritic cells (DCs) also negatively regulates T cell activation through different mechanisms, including STING- and TBK1-mediated ones, to prevent autoimmunity and exaggerated inflammation." (PMID 38339107, 2024).
colitis (4 papers, 2015 to 2023). Inflammation of the colon. "Following AOM/DSS challenge, Nlrc3−/− mice exhibited significantly higher colitis severity as well as CAC burden, with the majority of mice exhibiting features of adenocarcinoma whereas WT mice exhibited none." (PMID 37884500, 2023). "Karki R and colleagues show that mice lacking NLRC3 are hyper-susceptible to colitis and colorectal tumorigenesis." (PMID 30271661, 2018). "NLRP6 and NLRP12 have been found to attenuate NF-kB and MAPK in models of colitis and CRC, NLRC3 has been shown to act as a negative regulator of TLR and DNA-induced cytokine production." (PMID 26378020, 2015).
hepatocellular carcinoma (3 papers, 2022 to 2023). A malignant tumor that arises from hepatocytes. "JAK2/STAT3 signal pathway is associated with the suppressive effect of NLRC3 on hepatocellular carcinoma." (PMID 36341336, 2022). "In addition, NLRC3 silencing may play an important role in cancer progression and prognosis of hepatocellular carcinoma via the activation of Janus kinase 2/signal transducers and the transcription 3 (JAK2/STAT3) pathway under interleukin-6 (IL-6) stimulation." (PMID 37964222, 2023).
bladder cancer (2 papers, 2022). "Wnt/β-catenin signal pathway is associated with the suppressive effect of NLRC3 on bladder cancer." (PMID 36341336, 2022).
keratitis (2 papers, 2022). A corneal disease that is characterized by inflammation of the cornea. "The anti-inflammatory role of NLRC3 in P. aeruginosa induced keratitis suggested NLRC3 as a potential therapeutic target for PA induced keratitis." (PMID 35328532, 2022). "NLRC3 exerts beneficial roles in PA-induced keratitis.The expression of NLRC3 is decreased in mouse corneal tissue and macrophages cultured in vitro after PA infection." (PMID 36341336, 2022). "Decreased levels of proinflammatory cytokines and activation of the NF-κB signaling pathway were observed when NLRC3 was overexpressed and reduced P. aeruginosa induced keratitis progression." (PMID 35328532, 2022).
liver cancer (2 papers, 2020 to 2022). An epithelial or non-epithelial malignant neoplasm that arises from the liver. "In subsequent single-factor and multi-factor analysis, it was found that the NLRC3 level represents an independent prognostic indicator for liver cancer." (PMID 35145917, 2022). "Thus, not only does NLRC3 suppress the malignant progression of liver cancer but its level in cancer tissue can be used as a measure of malignancy in HCC." (PMID 35145917, 2022). "Therefore, NLRC3 may be an important factor affecting the malignant progression of liver cancer." (PMID 35145917, 2022). "In our study, we found that NLRC3 and IFI16 were independent prognostic factors for favorable OS in patients with liver cancer." (PMID 33006365, 2020). "However, there is no any significant relationships between NLRC3 and other clinical or pathological characteristics, including tumor differentiation, tumor size or number, TNM stage, Barcelona clinic liver cancer (BCLC) stage, tumor thrombus, tumor capsule, and history of cirrhosis." (PMID 35145917, 2022).
Sepsis (2 papers, 2021 to 2025). Sepsis is defined as life-threatening organ dysfunction caused by a dysregulated host response to infection. "In the context of sepsis, monocytes from 35 patients with bacterial sepsis presented significantly elevated NLRC3 levels compared with those from controls." (PMID 40153575, 2025).
Arthritis (1 paper, 2023). Inflammation of a joint. "Using an online Venn diagram tool, we then screened four genes related to dysregulated genes shared by TGT’s active ingredients and SLE and arthritis, including NLRC3, CD96, CCL2, and TLR1." (PMID 37312878, 2023). "We found that triptoquinone A and B, the active compounds in TGTs, could potentially prevent SLE-related arthritis onset by targeting NLRC3." (PMID 37312878, 2023).
autoimmune disease (1 paper, 2017). A disorder resulting from loss of function or tissue destruction of an organ or multiple organs, arising from humoral or cellular immune responses of the individual to their own tissue constituents. "NLRC3 (NLR family CARD domain containing 3), belongs to a large family of cytoplasmic sensors, regulating inflammatory and autoimmune diseases." (PMID 28883792, 2017).
Cerebral ischemia (1 paper, 2022). Restriction of arterial blood supply to the brain associated with insufficient oxygenation to support the metabolic requirements of the tissue. "Sevoflurane was observed to play beneficial roles on cerebral ischemia-reperfusion injury, and NLRC3 enhanced the beneficial effects of sevoflurane on ischemia-reperfusion models." (PMID 36341336, 2022).
colon cancer (1 paper, 2024). "In colon cancer, NLR family CARD domain containing 3 (NLRC3) interacts with PI3K, restraining the activation of the downstream molecule AKT." (PMID 38169510, 2024).
dementia (1 paper, 2022). Loss of intellectual abilities interfering with an individual's social and occupational functions. "The results suggest that rare variants in IFFO1, DTNB, NLRC3, and SLC22A10 heighten susceptibility to neuronal injury and inflammation, potentially by altering cytoskeleton structure and immune activity disinhibition, resulting in an elevated dementia risk." (PMID 35173266, 2022).
endometrial cancer (1 paper, 2019). Primary or metastatic malignant neoplasm involving the endometrium (mucous membrane that lines the endometrial cavity). "Among these survival-related genes, five genes (EPHB2, FBP1, NLRC3, PPP2R3A, and TRIM46) were included in a previously reported 9-gene signature for predicting endometrial cancer patient survival." (PMID 30847026, 2019).
hepatic diseases (1 paper, 2023). "A negative regulatory role of NLRC3 genes for the liver has previously been reported in hepatic diseases." (PMID 37964222, 2023).
HIV-1 infection (1 paper, 2020). The type species of lentivirus and the etiologic agent of acquired immunodeficiency syndrome (AIDS). "Consequently, NLRC3 might be involved in modulating cGAS/STING signaling during HIV-1 infection, although it is currently not known if HIV DNA binds to NLRC3 and promotes its dissociation from STING." (PMID 31968566, 2020).
Hypertension (1 paper, 2023). The presence of chronic increased pressure in the systemic arterial system. "Studies showed that biomarkers include PLD2, FLNA (filamin A), SMURF1, LINGO1, CACNA1H, NLRP6, NLRC3, CXCR2 and C5AR1 plays an important role in progression of hypertension." (PMID 36837510, 2023).
liver cirrhosis (1 paper, 2022). "Notably, it was observed that raised NLRC3 levels in HCC patients with a history of liver cirrhosis were linked to both overall and disease-free survival." (PMID 35145917, 2022). "Because NLRC3 is involved in inflammation response, the liver cirrhosis of HCC patients was taken into account." (PMID 35145917, 2022).
liver dysfunction (1 paper, 2021). "The Nlrc3−/− mouse model resembles systematic injury observed in humans, characterized by thrombocytopenia, lymphocytopenia, elevated serum levels of AST (liver dysfunction), LDH, creatine kinase MB fraction, and UA (renal dysfunction)." (PMID 34335602, 2021).
lung adenocarcinoma (1 paper, 2023). A carcinoma that arises from the lung and is characterized by the presence of malignant glandular epithelial cells. "However, the clinical relevance of NLRC3 in lung adenocarcinoma (LUAD) remains unclear." (PMID 36808166, 2023).